IGF1 (insulin like growth factor 1)
Diseases named in the same sentence as IGF1 in open-access papers (continued):
Sharing a sentence is not in itself a finding about the gene and the disease.
Sepsis (continued). "Because IGF-1 signaling is reduced by inflammatory cytokines and in sepsis, it is tempting to speculate that this mechanism contributes to muscle atrophy in sepsis." (PMID 34572540, 2021). "Sepsis and endotoxin administration also decrease IGF-1 expression in skeletal muscle." (PMID 34502376, 2021). "Moreover, production of IGF-1 protein in the lung was also reduced in the lungs of sepsis-surviving Il1rl1−/− or Stat6−/− mice." (PMID 28374774, 2017). "Finally, both atrogin-1 and MuRF1 mRNA increase with inflammation, as observed in the gastrocnemius of a rat model of sepsis, where it was upregulated in a dose- and time-dependent manner, and the increase was prevented by IGF-1 administration, but MuRF-1 was unchanged." (PMID 36904071, 2023). "Furthermore, local IGF-1 administration is able to prevent sepsis-induced skeletal muscle wasting." (PMID 34502376, 2021). "In sepsis, IGFBP-3 demonstrates IGF-1-independent effects, including the modulation of immune responses, regulation of apoptosis, and influence on inflammation." (PMID 40724799, 2025). "Several preclinical studies have demonstrated the feasibility and benefits of modulating IGF-1/IGFBP-3 expression in acute pathologies, including sepsis." (PMID 40724799, 2025). "qRT-PCR analysis showed that levels of IGF1, which promotes angiogenesis via VEGF signaling pathway, were downregulated in sepsis patients." (PMID 35187084, 2022). "Also, IGF1 serum levels at third week of life were significantly lower in those patients who developed bronchopulmonary dysplasia, needed any kind of mechanical ventilation or oxygen support, patent ductus arteriosus, sepsis in the first 3 weeks of life, EPO treatment or needed transfusion." (PMID 24523937, 2014). "False positives may be seen with sepsis and cachexia as both IGF-2 and IGF-1 are subnormal in these cases." (PMID 38432069, 2024). "Similarly, IGF-1 increase was inhibited by other stress or inflammation conditions as well: very low Apgar score, severe RDS and late sepsis." (PMID 37292373, 2023). "As apoptosis induces immunosuppression, the reduced expression of the anti-apoptotic genes (IGF1, GAMT) may have a role in the immune suppression phase of sepsis and support the concept of LPS induced immune regulation/paralysis." (PMID 28056766, 2017). "We have developed a method for the prediction of retinopathy of prematurity, based on serum levels of IGF1 in the third week and the presence or absence of sepsis in the first three weeks after birth." (PMID 24523937, 2014). "The graphs obtained give the probability of developing ROP of any stage with respect to serum IGF1 level in the third week post-partum and presence or absence of sepsis in the first three weeks." (PMID 24523937, 2014). "Sepsis may contribute to PGF by increasing energy expenditure and inducing a catabolic state that impairs lean mass and fat accumulation, while also disrupting IGF-1 levels essential for early postnatal growth." (PMID 40431467, 2025). "IGF-1 therapy prevented the sepsis-induced increase in MAFbx mRNA and did not affect MuRF1." (PMID 36904071, 2023). "Therefore, it was evident that the up regulation of GH failed to restore normal production of IGF-1 in sepsis mice, similar to human sepsis patients." (PMID 31791247, 2019).
breast tumors (57 papers, 1995 to 2024). "In this study, we have identified the protein S100A7 as novel molecular target of IGF-1 action in the breast tumor microenvironment, toward increased cancer-associated angiogenesis." (PMID 33557316, 2021). "Gene expression analysis of isolated cell populations revealed that TAMs are the main source of Igf-1 and that both TAMs and cancer-associated fibroblasts (CAFs) are major sources of Igf-2 in the breast tumor microenvironment." (PMID 29367764, 2018). "Analyses by breast tumor subtype revealed potential heterogeneity for rs2288378, representing the four high-LD IGF1 SNPs, decreasing risk of only ER+ and/or PgR+/HER2− tumors by approximately 45% among East Asian women." (PMID 27376028, 2016). "Our data are consistent with other studies that showed reduced circulating IGF1 levels can delay breast tumor onset and growth in IGF1‐deficient mice compared to WT mice." (PMID 26923183, 2016). "IGF-1 expression has been shown to be activated by estrogens whereas breast tumors with BRCA1 mutations demonstrate elevated IGF-1 levels." (PMID 25743390, 2015). "In earlier studies, we demonstrated increased insulin-like growth factor-I (IGF-1) is associated with breast tumor formation and poor clinical outcomes." (PMID 25062088, 2014). "Consistent with a positive effect of the IGF1 rs7965399 C allele on IGF1, this allele was also associated with a trend towards higher IGF1 concentration in breast tumours." (PMID 25117571, 2014). "The IGF1/IGF1R axis primes the breast tumor microenvironment toward the acquisition of an angiogenic phenotype through S100A7/RAGE signaling." (PMID 38892104, 2024). "The levels of the hallmarks of cell proliferation and angiogenesis involved in IGF-1/PI3K/Akt/GSK3β/β-catenin signaling pathway molecules were upregulated in obese rat breast tumors compared to lean rats." (PMID 37511200, 2023). "Five estrogen-responsive genes, CYP19A1, EGFR, ESR2, FOS, and IGF1, were found to be modified in human endometriosis, uterine tumor and breast tumor tissues." (PMID 36401252, 2022). "Beclin-1 expression inversely correlates with Akt and extracellular regulated kinase 1/2 (ERK) phosphorylation in human breast tumors through its Beclin-1-dependent regulation of insulin-like growth factor-1 (IGF-1) and EGF receptor trafficking." (PMID 35309939, 2022). "The IGF-1/IGF-1R pathway has a prominent oncogenic role in breast tumors, where it triggers direct autocrine proliferative and migratory actions on epithelial cancer cells." (PMID 33557316, 2021). "Altogether, these findings suggest that the IGF-1/IGF-1R axis primes the breast tumor microenvironment toward the acquisition of an angiogenic phenotype through the S100A7/RAGE signaling." (PMID 33557316, 2021). "Much evidence suggested that high animal protein intake can raise the circulating levels of insulin-like growth factor-1 (IGF-1) that plays an important role in breast tumor progression." (PMID 31333806, 2019). "Altogether, these results establish that HIF-1α/GPER signaling is required downstream of IGF1 for VEGF-mediated angiogenesis in the breast tumor microenvironment." (PMID 29212519, 2017). "Heterogeneity in odds ratios between breast tumour subtypes for select IGF1 pathway SNPs among European and East Asian women." (PMID 27376028, 2016). "For example, the mitogenic action of estrogen-receptor-positive, non-invasive breast tumor cells relies on the overproduction of WISP-2 by epidermal growth factor or insulin-like growth factor (IGF-1)." (PMID 25435966, 2015). "Note, insulin like growth factor 1 (Igf1) and insulin like growth factor binding protein 5 (Igfbp5) were decreased or unchanged in confounders but increased in breast tumor-bearing mice." (PMID 21589862, 2011). "Endothelin-1 (ET-1) levels are elevated in human breast tumours compared with normal and benign tissues, and in the presence of insulin-like growth factor 1 (IGF-I) ET-1 is a potent mitogen for human breast fibroblasts." (PMID 7880721, 1995).
breast tumors (continued). "IGF1 affects the incidence and mortality of tumors and survival from breast tumors." (PMID 35896848, 2022). "In this cotext, our study highlights that S100A7 may be considered as a novel angiogenic paracrine mediator of the IGF-1/IGF-1R action elicited in breast tumors." (PMID 33557316, 2021). "Based on their critical role in fetal growth and in the development of the mammary gland, IGF-1 and estrogen may play a role in the initiation and promotion of breast tumors." (PMID 32791983, 2020). "Moreover, exposure to the carcinogen 7,12-dimethylbenz(a)anthracene in dwarf rats that exhibit low levels of circulating IGF-1 produces fewer ERα-positive breast tumors than in normal rats." (PMID 30692633, 2019). "Moreover, IGF-1 stimulation protects against thapsagargin-induced EnR stress activity in MCF7 cells suggesting the IGF-1 signaling pathway augments the adaptability of breast tumor cells to EnR stress." (PMID 30458886, 2018). "In order to investigate the angiocrine actions of IGF1 in breast tumour, first of all we asked whether IGF1 induces the expression of VEGF and its transcriptional regulator HIF-1α in our experimental models." (PMID 29212519, 2017). "On the basis of the findings above that indicate that a functional interplay between HIF-1α and GPER regulates the expression of the key angiogenic mediator VEGF, we next evaluated the contribution of HIF-1α/GPER signaling to the stimulatory response induced by IGF1 in breast tumor microenvironment." (PMID 29212519, 2017). "Interestingly, in human breast tumor samples, GPER expression correlates with IGF1R and with the vessel marker CD34, corroborating the engagement of GPER and IGF1 system in breast tumor angiogenesis in breast tumor microenvironment." (PMID 29212519, 2017). "Our finding of augmented IGF-1 among women with low body mass may have implications for understanding breast tumor heterogeneity in diverse populations and should be evaluated in larger prospective studies with cancer outcomes." (PMID 26352264, 2015). "IGF1 was expressed in 30% of breast tumors, IGF1R in 26%, IGFBP2 in 74%, and IGFBP3 in 32%." (PMID 25619494, 2015). "Analysis of 965 primary breast tumors from TCGA RNA‐seq dataset showed that breast tumors harboring H1047R and other PIK3CA mutations (including E545K and E542K) have significant upregulation of AXIN2, HGF, STAT3, IGF‐1, and IGF‐2 mRNA compared with PIK3CA‐wild‐type and HER‐2‐amplified tumors." (PMID 28296140, 2017). "These large, independent patient datasets, comprising 4972 breast tumors, suggested to us that GPER, IGF1/IGF1R signaling and blood vessel density (CD34) are correlated, and that GPER and IGF signaling may be linked to changes in the breast tumor microenvironment." (PMID 29212519, 2017). "We established that the IGF-1/IGF-1R axis triggers STAT3-dependent transcriptional activation of S100A7, which acts as a paracrine mediator in the breast tumor microenvironment." (PMID 33557316, 2021). "RCC2 expression upregulated IL-6, IGF1, and TWIST1 expression both in animal models and in cultured ER + breast tumor cells." (PMID 32565805, 2020). "For instance, there was a significant correlation between PI3K/IGF1 gene set signature scores and high PRR11 mRNA levels in clinical cohorts of ER+ breast tumors treated with neoadjuvant letrozole." (PMID 33127913, 2020). "At least 50% of breast tumors present with activated IGF-1R and the level of circulating IGF-1 positively correlates with the incidence of estrogen receptor positive (ER positive) breast tumors." (PMID 32435229, 2020). "We recently showed that TAMs and CAFs are the main sources of Insulin-like growth factors 1 and 2 (IGF-1, IGF-2) in pancreatic and breast tumors, and that IGF signaling mediates resistance of murine pancreatic and breast tumors to gemcitabine and paclitaxel." (PMID 30356656, 2018).
breast tumors (continued). "IGF-1 is considered to be a strong mitogen for BC cells and IGF-1 receptors are expressed in breast tumour tissues 10 folds higher than normal breast tissues." (PMID 30048498, 2018). "Estimated using the ssGSEA (single sample gene set analysis) method, PIK3CA‐mutant breast tumors showed activated AKT, IGF1‐mTOR, and WNT canonical signaling pathways compared to PIK3CA‐wild‐type and HER2‐overexpressing tumors." (PMID 28296140, 2017). "Taken together these findings suggest that IGF1/IGF1R axis engages ERK1/2 and AKT signaling to trigger the activation of HIF-1α/GPER/VEGF transduction pathway in breast tumor microenvironment." (PMID 29212519, 2017). "At the cellular level, insulin as well as IGF-1 dramatically synergizes with GPCR agonists in inducing mitogenic signaling in multiple solid tumors including pancreas, colon, prostate, and breast tumors." (PMID 25798130, 2015). "Indeed, breast tumors may aberrantly express each component of the IGF-1 system." (PMID 25743390, 2015). "In multiple in vivo breast tumor models, non-immune stromal cells and tumor-associated macrophages (TAM), but not tumor cells, primarily express Igf1 and Igf2 mRNA." (PMID 36556357, 2022). "Insulin and insulin-like growth factor-1 (IGF-1) are the most important negative regulators of the sex hormone-binding globulin (SHBG) synthesis pathway in vitro and may lead to the development of breast tumors in a variety of ways." (PMID 35464024, 2022). "In view of the fact that IGF1 is mainly produced by stromal cells whereas IGF2 biosynthesis occurs directly in breast tumor cells, data indicate that BRCA1 gene expression is potentially regulated by both autocrine (IGF2) and paracrine/endocrine (IGF1) stimuli." (PMID 35432218, 2022). "The core importance of IGF-1 in the pathogenesis of BBD which mediates the interaction between metabolic variables and the proliferation of breast benign neoplasm provides modifiable circumstances for life-style related interventions for which the area is widely remained to be resolved." (PMID 31752829, 2019). "It should be mentioned that in our gene data, obtained from the integrated bioinformatic analysis of human breast tumor samples, IGF1 and VEGF are not positively correlated with the expression of GPER." (PMID 29212519, 2017). "Interestingly, the expression levels of PTGS2 (-4.80-fold change) and EGFR (-2.45-fold change) regulated by hsa-mirR128, ABCB1 (-2.21-fold change), IGF1 (-2.19-fold change), and IL6 (-2.85-fold change) regulated by hsa-miR-223, were significantly reduced in breast tumour tissue." (PMID 32577155, 2020). "mRNA expression fold changes in DEGs of breast tumors with high AGR2 compared to those with low AGR2 were consistent with prior findings highlighting the roles of intracellular and extracellular AGR2 in tumorigenesis pathways mediated by estrogen signaling and Insulin Growth Factor 1 (IGF-1)." (PMID 29796176, 2018). "Thus, IGF-1, possibly through the involvement of other molecules, cross-talks with the Wnt/β-catenin pathway, via both AKT and/or ERK signaling, promoting migration of breast tumors." (PMID 25743390, 2015). "Moreover, it has recently been postulated that mesenchymal stromal cells in the microenvironment of primary breast tumors preselect carcinoma subclones with a high bone tropism via secretion of stromal cell-derived factor 1 (SDF-1) and insulin-like growth factor 1 (IGF-1)." (PMID 25909161, 2015). "Therefore, S100A7 may represent a novel effector through which the IGF-1 system executes molecular programs that modulate the breast tumor microenvironment toward the acquisition of negative features (as depicted in the graphical abstract)." (PMID 33557316, 2021).
breast tumors (continued). "Furthermore, our data regarding the integrated bioinformatic analysis of gene expression studies from human breast tumor samples, evidence that GPER and the IGF1/IGFIR system may be regarded as a peculiar angiocrine signature, for their co-expression pattern with the microvessel-density marker CD34." (PMID 29212519, 2017). "Using copy-number and sequencing data of a large cohort of 171 breast tumours (38 metastasized, 130 no-metastasis) we observed an increased frequency of losses in those tumours that metastasized for many of the top ranked genes including BCL2 (18% vs 13%), IGFBP7 (11% vs 6%), IGF1 (8% vs 2%)." (PMID 20673354, 2010).
hypogonadism (57 papers, 2006 to 2025). A disorder characterized by decreased function of the gonads. "Within the low BMD subgroup, hypogonadism, serum phosphate and low serum IGF-1 levels were associated with a lower Z-score." (PMID 38978629, 2024). "In the low BMD subgroup, hypogonadism was associated with a lower Z-score at the lumbar spine, while serum phosphate and low serum IGF-1 levels were associated with a lower Z-score at the femoral neck." (PMID 38978629, 2024). "Every regression model included age, sex, diagnosis (CD vs. NFPA), untreated hypogonadism (primary + secondary), average dosage of hydrocortisone replacement, untreated GH deficiency, IGF-1 and FLI scores as independent variables." (PMID 27194386, 2016). "The development of hypogonadism is associated with the transition to severe weight loss in addition to marked reduction in muscle IGF-1 and increased proteolysis." (PMID 24285707, 2013). "This reduction in IGF-1 results in systemic problems including muscle atrophy, osteopenia, hypogonadism, protein-calorie malnutrition, weight loss, and many others." (PMID 19344517, 2009). "Multivariate analysis consistently identified advancing age as an independent risk factor for low bone mass, normal BMI and ALB as protective factors, while IGF-1 levels < -2 SD and hypogonadism demonstrated significant risk associations in the uncorrected model." (PMID 40671911, 2025). "Given that the decrease in IGF-1 can be >2 SD in some patients and potentially clinically significant, we recommend interval monitoring of serum IGF-1 levels and symptoms of growth hormone deficiency in patients with hypogonadism treated with clomiphene citrate." (PMID 40421427, 2025). "Impaired hepatic synthesis of IGF-1 due to deficient growth hormone (GH) secretion, hepatic iron overload, and inadequate nutrition may contribute to hypogonadism in patients with β-thalassemia." (PMID 38003451, 2023). "The corrected model further identified normal BMI (OR=0.383) and ALB (OR=0.866) as protective factors, while IGF-1 levels < -2 SD (OR=1.832) and hypogonadism (OR=2.990) emerged as significant risks in the uncorrected model." (PMID 40671911, 2025). "Multivariate analysis identified age (OR = 1.149, 95% CI 1.052–1.256, P < 0.05), IGF-1 levels < -2 SD (OR = 1.832, 95% CI 1.095–3.067, P < 0.05), and hypogonadism (OR = 2.990, 95% CI 1.087–8.229, P < 0.05) as independent risk factors for low bone mass." (PMID 40671911, 2025). "Determinants of low bone density in patients with AN include hypogonadism, low BMI, low lean body mass, low IGF-1, and GH resistance." (PMID 41024930, 2025). "It must also be noted that enrolled patients had a controlled disease with normal levels of GH/IGF-1, possibly explaining the low presence of hypogonadism." (PMID 37306894, 2024). "On the other hand, IGF-1 levels negatively correlated with the presence of biochemical hypogonadism (Spearman’s ρ = − 0.585; p = 0.028)." (PMID 37306894, 2024). "Patients presenting with preoperative hypogonadism exhibited elevated baseline concentrations of GH and IGF-1." (PMID 39337013, 2024). "Among patients with low BMD, we observed a correlation between a Z-score with low IGF-1 levels (β=-0.42; 95% CI -0.83 to -0.01; p=0.040), serum phosphate levels (β=0.40; 95% CI 0.07 to 0.73; p=0.016) and hypogonadism (β=-0.48, 95% CI -0.91 to -0.04, p=0.031)." (PMID 38978629, 2024). "The study findings indicated that individuals with hypogonadism had significantly lower IGF-1 levels than those with eugonadism." (PMID 37775530, 2023). "Low BMD in AN is considered multifactorial and related to lower BMI, lower lean mass, hypogonadism, Growth Hormone resistance and low IGF-1, high cortisol levels, high PYY levels, and low levels of leptin, oxytocin, insulin and amylin." (PMID 37393263, 2023). "Some studies have identified that GH or IGF-1 levels or hypogonadism are correlated with fat and lean mass." (PMID 35355553, 2022).